REN (renin)
Diseases named in the same sentence as REN in open-access papers (continued):
Sharing a sentence is not in itself a finding about the gene and the disease.
diabetes (continued). "Although the exact causes of primary hypertension remain unclear, several factors that increase the risks of primary hypertension have been identified: hypercholesterolemia, diabetes, increased physiological production of renin and an imbalanced sexual hormones profile." (PMID 19865517, 2009). "We previously showed that male preterm mice with diabetes develop early features of DKD, including reduced podocyte density, decreased renin expression, activation of angiogenesis pathways, and impaired endothelial-podocyte signaling." (PMID 42008787, 2026). "Research indicates that the activation status of the renin-angiotensin-aldosterone system (RAAS) undergoes alterations in Type 1 and Type 2 diabetes mellitus (T1DM/T2DM) patients with various complications." (PMID 40106408, 2025). "Background/Objectives: Disrupted intracellular calcium (Ca2+i) regulation and renin–angiotensin system (RAS) activation are pathogenetic factors in diabetic cardiomyopathy, a major complication of type 1 (T1D) and type 2 (T2D) diabetes." (PMID 40149735, 2025). "At randomisation, the mean age was 60.1 ± 10.5 years, 616 (51.5%) were men, the median duration of diabetes was 10 (5.0–16.0) years, 35.6% achieved ≥2 ABC targets, 83.9% were on statin, and 61.5% were on renin‐angiotensin system inhibitors (RASi)." (PMID 40954936, 2025). "In individuals with diabetes, RAAS is often upregulated, leading to elevated plasma renin, increased arterial pressure, and heightened renal vascular resistance." (PMID 40725728, 2025). "Association of percentage of crossing capillaries with maximum lifetime BMI adjusted for age, sex, regular exercise, duration of diabetes, HbA1c level, DBP, renin-angiotensin system inhibitor use, lipid-modifying medication, and BMI at the time of the survey." (PMID 39781172, 2024). "As a long-term effect of the current standard treatment of diabetes and CKD, i.e. blocking of the renin-angiotensin system, remains unaddressed, an interesting study has tried to model the possible impact of “early” and “late” intervention." (PMID 36908289, 2023). "Upregulation of angiotensin-converting enzyme 2 (ACE2), a key member of the renin–angiotensin system (RAS), is in general protective against cardiovascular diseases and diabetes." (PMID 37106756, 2023). "In conclusion, diabetes produces morphological changes in the intestines, increases plasma SCFA, and alters the expression of renin and MasR." (PMID 35682739, 2022). "Plasma renin activity and angiotensins were reported to be increased in advanced liver disease which indicates the role of RAAS in diabetes-induced liver impairment." (PMID 36316746, 2022). "Aliskiren is a direct renin inhibitor, that prevents the formation of Ang II by blocking renin from converting to Ang I. Our study is the first to demonstrate the hepatoprotective impacts and mechanisms of aliskiren in a model of STZ-induced diabetes in mice." (PMID 36316746, 2022). "For almost two decades, the management of patients with type 2 diabetes mellitus (T2DM) and chronic kidney disease (CKD) was based on the optimal glycemic and blood pressure control as well as on the adequate blockade of the renin-angiotensin-system." (PMID 35207711, 2022). "It is also evident in the current meta-analysis that combination therapy of direct renin inhibitors and ARB is more effective in decreasing the progression of kidney disease among patients with diabetes." (PMID 36204481, 2022). "Therefore, it would be interesting to investigate whether diabetes is responsible for this increased intrarenal renin and accompanying kidney injury, or rather that this increased intrarenal RAS, as with diabetes, is in fact an concomitant result of the aging process." (PMID 34830315, 2021). "Hyperkalemia has been linked to several factors including reduced eGFR, treatment with renin–angiotensin–aldosterone system (RAAS) blockers and a cellular shift due to the presence of acidosis or diabetes." (PMID 34532036, 2021).
diabetes (continued). "At baseline, renin (plasma renin activity, PRA) was increased from normal to glucose tolerance and more in diabetes, also correlating with ferritin." (PMID 34107965, 2021). "Therefore, some patients with diabetes who are inverse salt-sensitive and follow national federal guidelines for lower sodium consumption may have elevated blood pressure by activation of renin-aldosterone and sympathetic nerve systems, leading to the development of vascular complications." (PMID 33670045, 2021). "The renin–angiotensin–aldosterone system (RAAS) component ACE2 and DPP4 are proteins dysregulated in diabetes." (PMID 32848769, 2020). "Our recent demonstration showed that angiotensin II receptor distribution is related to renin granulation in normal and STZ-induced diabetes." (PMID 31049226, 2019). "It is believed that the use of ACEI/ARB for patients with diabetes as the first choice of antihypertensive drugs in general may protect against the fibrotic changes in the left ventricle, since increased activation of the renin-angiotensin-aldosterone pathway leads to fibrosis formation." (PMID 28683825, 2017). "Raw garlic aqueous extract (GE) has ameliorative actions on the renin-angiotensin system in type-1 diabetes mellitus (DM); however its effects on plasma and kidney angiotensin I converting enzyme type-1 (ACE-1) and angiotensin II (AngII) require further elucidation." (PMID 27293465, 2016). "Medications aimed at inhibiting the renin–angiotensin system (RAS) have been used extensively for preventing cardiovascular and renal complications in patients with diabetes, but data that compare their clinical effectiveness are limited." (PMID 26954482, 2016). "Medications aimed at inhibiting the renin–angiotensin system (RAS) have been used extensively for preventing cardiovascular and renal outcomes in patients with diabetes." (PMID 26954482, 2016). "The renin-angiotensin system (RAS) modulates inflammation in a variety of clinical conditions including cancer, diabetes and rheumatoid arthritis." (PMID 26244896, 2015). "We measured AGT and renin expression and ANG II concentration in cardiac myocytes isolated from AT1a-KO mice after one wk of diabetes." (PMID 24215514, 2013). "Numerous animal and clinical investigations have pointed to a potential role of the renin-angiotensin system (RAS) in the development of insulin resistance and diabetes in conditions of expanded fat mass." (PMID 23308073, 2012). "For patients with HTN and CKD with or without diabetes, renin-angiotensin-aldosterone inhibitors are first line agents." (PMID 40932828, 2025). "Superficial vessels have a closer coupling with retinal ganglion cells, and their signaling pathways are more affected by the renin - angiotensin system in diabetes and renal impairment, unlike deep vessels which are more influenced by local factors." (PMID 41291794, 2025). "Interestingly, it has been confirmed that hyperglycemia in diabetes patients can activate the intrarenal RAAS system, which induced the release of the renin and angiotensin (Ang)." (PMID 38020922, 2023). "Furthermore, diabetes and obesity could both induce decreased kidney function due to interactions among multiple metabolic and hemodynamic factors, including activation of the renin angiotensin aldosterone system and sympathetic nervous system, kidney compression, and dyslipidemia." (PMID 36069056, 2023). "In this model, diabetes induction increased prorenin rather than renin, in agreement with observations in humans that diabetes is characterized by high prorenin levels and low‐to‐normal renin levels." (PMID 36106615, 2023). "Blockade of the renin-angiotensin system with ACE inhibitors has already been shown to have analgesic effects in humans and in several models of neuropathic pain induced by chronic constriction injury, insulin resistance, or streptozotocin-diabetes." (PMID 35456682, 2022).
diabetes (continued). "Ang IV and its receptor AT4R overactivation in the renin-angiotensin system (RAAS) and cardiomyocyte autophagy abnormalities may be important mechanisms by which diabetes leads to myocardial injury and ventricular remodeling." (PMID 36699083, 2022). "Although generally the circulating RAS is up in CKD, it is not in patients with diabetes, whose plasma renin levels are low." (PMID 35710133, 2022). "The direct renin inhibitor was not better than the control group in reducing eGFR in diabetes patients." (PMID 36204481, 2022). "Renin–angiotensin–aldosterone system (RAAS) blockers (angiotensin-converting enzyme inhibitors (ACEI) and angiotensin receptor blockers (ARB)) are generally used in patients with cardiovascular disease, CKD, and diabetes." (PMID 35054347, 2022). "Differentially regulated genes not overlapping with ERCB data also reflected diabetes-associated changes, such as extracellular matrix (ANGPTL4, TNN, DPT, COL9A2) or gestational diabetes (LAT2, HP, CXCL10, CD86, CD68, REN, SLC2A3, VCAM1)." (PMID 33923831, 2021). "In the sub-group analysis, mortalities in patients with age < 75, diabetes, dyslipidemia, atrial arrhythmia, cancer, renin-angiotensin system blocker, and β-blocker were not affected by vitamin D supplementation." (PMID 33498709, 2021). "However, only 15.4, 29.5 and 44.9% of those with diabetes-related LLA were on lipid-lowering, antiplatelet and renin-angiotensin-aldosterone inhibitor therapy at baseline." (PMID 30823912, 2019). "The plasma and intrarenal renin is found to be activated early in diabetes; yet the exact mechanism is not known." (PMID 29445185, 2018). "Empagliflozin treatment increased plasma renin activity in non-diabetic mice, and both empagliflozin (P = 0.059) and metformin mono-therapies exacerbated this diabetes-induced increase." (PMID 27226136, 2016). "This is higher than the rate of renin-angiotensin blockade in an urban sample of both Indigenous Australians with diabetes (47%) and non-Indigenous Australians with diabetes (66%)." (PMID 25884441, 2015). "The increasing response of renin granules co-localized in prominent JGA hyperplasia should be worried while physicians treat hypertensive patients with potent RAS inhibitors and diuretics even though they have diabetes." (PMID 28509110, 2015). "While we did not perform glucose tolerance tests on either TTRhRen or HD mice, blood glucose levels were invariably similar within non-diabetic or diabetic groups, suggesting that diabetes was induced equivalently irrespective of transgenic renin expression." (PMID 25514595, 2014). "The presence of renin-angiotensin aldosterone in adipose tissue has been described in which Ang II increased NADPH oxidase activity and WAT mediated inflammation and blocked RAAS thereby preventing the onset of diabetes." (PMID 23762544, 2013). "Considering the role of the renin–angiotensin–aldosterone system (RAAS) in diabetic complications, this study examined whether aldosterone (ALDO) and the mineralocorticoid receptor (MR) contribute to diabetes-related skin microangiopathy." (PMID 41511372, 2026). "For example, while lipid modifying agents, agents acting on the renin-angiotensin system and drug used in diabetes were again frequent medication classes, there was no evident increase in the proportion of users beyond the trajectory of “high users of medications”." (PMID 37408840, 2023). "There is a disagreement regarding the effect of factors such as obesity and diabetes on ACE2 expression in the human heart and whether treatment with renin–angiotensin system inhibitors or anti-diabetic medications increases ACE2 expression and subsequently the susceptibility to infection." (PMID 33906662, 2021).
diabetes (continued). "The association between stage 1 uncontrolled blood pressure and COVID-19–related death was only present in older patients (70+ years), those without a history of diabetes, chronic kidney disease, or cardiovascular disease, and those prescribed renin-angiotensin system medications." (PMID 33325240, 2021). "Our and other studies evidencing a diabetes-induced low-renin status may indicate that a DRI is not always effective in treating DN." (PMID 32231590, 2020). "Inhibition of the renin–angiotensin–aldosterone system (RAAS) with angiotensin converting enzyme inhibitors (ACEI) or angiotensin receptor blockers (ARB) significantly reduces albuminuria in diabetes, but this effect is not observed in all those treated." (PMID 29665833, 2018). "However, the performance of aldosterone to renin ratio (ARR) in primary aldosteronism (PA) patients with diabetes has not been well validated." (PMID 30332741, 2018). "Renin-angiotensin aldosterone system blockade with angiotensin converting enzyme inhibitors or angiotensin receptor blockers has been reported to attenuate diabetes-related cardiac dysfunction without significantly affecting blood pressure." (PMID 29290979, 2017). "Hence, in the present study, we investigated first the roles of intracellular renin (int-renin) on activation of signal molecules in ischemic resistance of diabetes mellitus (DM) hearts and second the contribution of mPTP to int-renin-mediated ischemic resistance in DM hearts." (PMID 29295576, 2017). "Renin was analyzed by the Proximity Extension Assay in subjects with (n = 985) and without (n = 515) T2D participating in the SUMMIT (SUrrogate markers for Micro- and Macro-vascular hard endpoints for Innovative diabetes Tools) study and in 205 carotid endarterectomy patients." (PMID 27596252, 2016). "The enhanced downregulation of the AT1-B receptors in the renin-negative SMCs in the efferent arterioles demonstrates that the regulation of the glomerular filtration rate by the pre- and postglomerular arterioles is changed in diabetes." (PMID 24587998, 2014). "The enhanced downregulation of AT1-B in the renin-negative SMCs of the efferent arterioles demonstrates that the regulation of the glomerular filtration rate by the pre- and postglomerular arterioles is changed in diabetes." (PMID 24587998, 2014). "Further studies are required to investigate whether circadian rhythms in specific markers (sympathovagal reactivity, platelet aggregability, blood viscosity, plasma renin activity, etc.)may yield a pattern of DBP circadian time structure as observed in diabetes mellitus." (PMID 23245213, 2012). "Group 1 had a higher proportion of male patients and a lower proportion of diabetes mellitus (DM), myocardial infarction (MI), or congestive heart failure (CHF), and administered renin–angiotensin system blockers, aspirin, or clopidogrel than those in the other groups." (PMID 38675457, 2024). "Inhibition of the renin-angiotensin-aldosterone system with an angiotensin converting enzyme inhibitor (ACEI) or an angiotensin II receptor blocker (ARB) delays CKD progression in patients with or without diabetes and stage 1–3 CKD, and also in patients without diabetes with stage 4 CKD." (PMID 32096480, 2020). "In this study, we investigated the roles of ns-renin and mitochondrial extracellular signal-related kinase (ERK) 1/2 on mitochondrial permeability transition pore (mPTP) opening during ischemia in diabetes mellitus (DM) hearts." (PMID 29295576, 2017). "Concretely, KDIGO recommends starting renin–angiotensin system inhibitors (RASis) for individuals with CKD and moderately to severely increased albuminuria with or without diabetes." (PMID 40428801, 2025). "The AT1-A receptors were downregulated equally in the renin-positive and renin-negative SMCs, while in diabetes the significant difference in the number of AT1-A receptors between the renin-positive and renin-negative SMCs was unchanged." (PMID 24587998, 2014).
diabetes (continued). "Consequently, the Kidney Disease: Improving Global Outcomes (KDIGO) 2024 Clinical Practice Guideline recommends avoiding any combination of ACEi, ARB, and direct renin inhibitors in patients with CKD, regardless of diabetes status." (PMID 40498214, 2025). "In univariate analysis, characteristics prior to admission significantly associated with the primary outcome were sex, BMI and previous treatment with renin–angiotensin–aldosterone system (RAAS) blockers, but not age, type of diabetes, HbA1c, diabetic complications or glucose-lowering therapies." (PMID 32472191, 2020). "As CPAP treatment was shown to downregulate renin-angiotensin-aldosterone activity and reduce VEGF levels in those without diabetes, these could possibly be mechanistic pathways by which CPAP use is associated with reduced risk of DKD and retinopathy." (PMID 29707586, 2018). "All patients with CKD should receive the maximum tolerated dose of a renin–angiotensin–aldosterone system inhibitor (RAASi), such as an angiotensin-converting enzyme inhibitor (ACEi) or an angiotensin II receptor blocker (ARB), and an SGLT2i, regardless of the presence of diabetes." (PMID 40283662, 2025). "Thus, in the patients with diabetes in ACTION, “reliance” may have been placed on the putative cardioprotective properties of drugs blocking the renin-angiotensin system (RAS blockade) rather than the attainment of improved BP control." (PMID 21274458, 2011).